BTK (Bruton tyrosine kinase)
Diseases named in the same sentence as BTK in open-access papers (continued):
Sharing a sentence is not in itself a finding about the gene and the disease.
neuroblastoma (11 papers, 2019 to 2023). Neuroblastoma (NB) is the most common solid, extracranial childhood tumor. "Neuroblastoma cells also express BTK, and high expression corresponds with poor neuroblastoma relapse-free survival." (PMID 36903645, 2023). "A previous study has shown BTK protein expression in neurons in the mouse brain and in a human neuroblastoma cell line." (PMID 38022591, 2023). "We found that BTK is also expressed in B cells as well as in TAMs isolated from mice bearing neuroblastoma tumors." (PMID 33669187, 2021). "Pikatan and colleagues found high percentages of cells with strong BTK expression in undifferentiated (57.1%) and poorly differentiated neuroblastoma (88.7%) and suggested BTK as a potential biomarker of neuroblastoma differentiation status." (PMID 34164404, 2021). "Increased expression of BTK correlates with a poor relapse-free survival probability in patients with neuroblastoma." (PMID 34485307, 2021). "Our study has shown that BTK is mainly expressed in MDSCs, B cells, and TAMs isolated from mice bearing neuroblastoma tumors." (PMID 33669187, 2021). "In BTK highly expressed primary neuroblastoma samples, BTK inhibitor acalabrutinib elicited remarkable effect on inhibition of neuroblastoma tumorigenesis." (PMID 32984343, 2020). "Moreover, the analyses of two different microarray datasets confirmed BTK overexpression in neuroblastoma patients which significantly correlated with a worse 3-year overall survival (OS)." (PMID 34164404, 2021). "The role of BTK in neuroblastoma tumorigenesis has been reported recently." (PMID 33669187, 2021). "In addition, they reported that high expression of BTK correlates with poor relapse-free survival probability of neuroblastoma patients." (PMID 34164404, 2021). "In this study it was assumed that the BTK expressed in neuroblastoma was the 77 kDa isoform." (PMID 34164404, 2021). "In addition, they showed that pharmacologic or genetic inhibition of BTK reduced neuroblastoma cells survival and their migratory and invasive abilities in vitro and reduced tumor growth in vivo." (PMID 34164404, 2021). "Interestingly, we find higher expression of BTK only in B cells, tumor-associated macrophages (TAMs), and MDSC isolated from neuroblastoma tumors." (PMID 33669187, 2021). "To note, high BTK expression occurred preferentially in MYCN-amplified neuroblastoma cases." (PMID 34164404, 2021). "In addition to the contradictory observations in BTK expression, these three groups also reported contradictory effects of ibrutinib on neuroblastoma cell lines." (PMID 34778053, 2021). "For instance, ibrutinib, an irreversible molecular inhibitor of Bruton's tyrosine kinase (BTK), was shown to reverse T cell suppression mediated by murine MDSC in a neuroblastoma mouse model." (PMID 38087370, 2023). "We found that the expression of both BTK and monocyte marker CD14 is elevated in various neuroblastoma cohorts compared to benign neurofibroma (Miller, N = 86)." (PMID 33669187, 2021). "Furthermore, we examined the prognostic significance of BTK expression and found that increased expression of BTK significantly correlates with worse overall survival (OS) in the non-MYCN amplified neuroblastoma cohort (Seeger dataset)." (PMID 33669187, 2021). "The expression of BTK in neuroblastoma cell lines and tumor tissues has been recently reported, but its role in the immune microenvironment and MDSC of NB are unknown." (PMID 33669187, 2021).
pemphigus (11 papers, 2018 to 2025). Pemphigus is a group of rare autoimmune diseases that cause blistering of the skin and mucous membranes (mouth, nose, throat, eyes, and genitals).This conditioncan occur at any age, but often strikes people in middle or older age. "In autoimmune skin diseases with pathogenic autoantibodies (e.g., pemphigus), BTK inhibition has shown promise by reducing B cell activation and autoantibody-mediated tissue injury." (PMID 40981278, 2025). "Bruton's tyrosine kinase (BTK)-dependent signaling pathway is claimed to have a significant role in the pathogenesis of autoantibody-driven dermatological conditions like pemphigus." (PMID 38125430, 2023). "In this study, we aim to provide a comprehensive review of current evidence and future prospects of BTK inhibitors in the treatment of different types of pemphigus." (PMID 38125430, 2023). "Rilzabrutinib and tirabrutinib are reversible and selective oral BTK inhibitors that are considered for treating pemphigus and have shown acceptable safety and efficacy profiles." (PMID 38125430, 2023). "The current review indicates that BTK inhibitors alone or in combination with conventional treatments are promising options in the management of pemphigus." (PMID 38125430, 2023). "Here, we discuss the current status and future prospects of treatment strategies for pemphigus, focusing mainly on rituximab and Bruton's tyrosine kinase (BTK) inhibitors, which are expected to become essential in the future treatment of this disease." (PMID 36478455, 2023). "Several clinical trials of the BTK inhibitors rilzabrutinib and tirabrutinib for pemphigus have been conducted." (PMID 36478455, 2023). "We declare the mechanism of action, safety, efficacy, challenges, and side effects of BTK inhibitors as novel therapeutic options in patients with pemphigus." (PMID 38125430, 2023). "All these findings bold BTK inhibitors as potential therapeutic choices for patients challenging with pemphigus and pemphigoid disorders." (PMID 38125430, 2023). "BTK inhibitors alone or in combination with conventional treatments such as CS were reported to be promising in the management of pemphigus." (PMID 38125430, 2023). "From the efficacy of RTX it is clear that B cells are an effective target for pemphigus treatment, and BTK is expected to be an important target for therapeutic interventions without depleting B cells." (PMID 36478455, 2023). "Some pre-clinical studies evaluated the effectiveness of BTK inhibitors in treating pemphigus in animal models." (PMID 38125430, 2023). "Two randomized clinical trials were conducted regarding the use of BTK inhibitors in patients with pemphigus." (PMID 38125430, 2023). "In this mini review, we present evidence regarding the mechanisms affected by BTK inhibition and the concept of BTK inhibition as an emerging new treatment in pemphigus." (PMID 34447768, 2021). "•Administration of reversible BTK inhibitors alone or in addition to conventional treatments can be promising combinations in managing pemphigus due to their high response rate, mild and limited side effects, and acceptable results in terms of safety and efficacy." (PMID 38125430, 2023). "BTK signaling pathway has been detected in the pathogenesis of pemphigus." (PMID 38125430, 2023). "Although the therapeutic efficacy of BTK inhibitors in pemphigus may be less pronounced when contrasted with rituximab, it is foreseeable that their continued advancement and exploration will persist in the future." (PMID 38125430, 2023). "There is a great deal of interest in the application of inhibitors of BTK in pemphigus treatment." (PMID 36478455, 2023). "Consequently, BTK inhibitors are under investigation as newly emerged therapeutic options for immunobullous disorders such as pemphigus and pemphigoid disorders." (PMID 38125430, 2023). "BTK inhibitors are currently in phase II clinical trials for pemphigus (NCT02704429)." (PMID 31975370, 2020).
pemphigus (continued). "Furthermore, enhanced expression of BTK in B-cells induces differentiation of T follicular helper cells, which have been shown to be involved in the pathogenesis of pemphigus." (PMID 31293582, 2019). "Bruton kinase (BTK) inhibitors are also a promising B-cell targeting therapy in pemphigus." (PMID 31293582, 2019). "Inhibition of Bruton's tyrosine kinase (BTK), a protein essential for B cell development, is an appealing therapeutic strategy for pemphigus based on the dual mechanism of action to block autoantibody production as well as to quickly dampen inflammation by inhibiting B cell activation." (PMID 30467542, 2018). "Therefore, BTK inhibitors were found to be beneficial alternatives to conventional treatmentsThe current study aimed to assess the efficacy and safety of BTK inhibitors in treating pemphigus." (PMID 38125430, 2023). "Furthermore, low MW inhibitors of Bruton tyrosine kinase (BTK), which is essential for B cell activation and maturation (Corneth, Klein Wolterink, & Hendriks, 2016), have been successfully evaluated in a phase I clinical trial in pemphigus patients." (PMID 32815159, 2020). "Among them, PRN1008 (rilzabrutinib) is a BTK inhibitor that was safe and well-tolerated following oral administration, and the report of a phase I study treated with PRN1008 demonstrated that PRN1008 could be effective on pemphigus." (PMID 35783635, 2022).
chronic myeloid leukemia (10 papers, 2013 to 2024). "Compound 7 in the series, comprising an ibrutinib-related BTK inhibitor retaining the acrylamide group linked to a VHL-targeting moiety, induced BTK degradation in K562 cells (derived from chronic myelogenous leukemia) with a DC50 of ~150 nM in an 18 h assay." (PMID 32924028, 2020). "Somatic gain-of-function mutations in BTK have also been identified in colorectal carcinoma, acute lymphoblastic leukemia (ALL), and chronic myeloid leukemia (CML)." (PMID 23958373, 2013). "However, rituximab and BTK inhibitor treatment were correlated significantly with a negative vaccination response, whereas younger age and chronic myeloid leukemia (CML) disease were associated with positive response." (PMID 35597847, 2022). "Of note, other tyrosine kinase inhibitors such BTK and BCR-ABL inhibitors have been clinically used to treat B-cell malignancies and chronic myeloid leukemia by inducing efficient cancer cell death." (PMID 36329033, 2022).
follicular lymphoma (10 papers, 2020 to 2025). Follicular lymphoma is a form of non-Hodgkin lymphoma characterized by a proliferation of B cells whose nodular structure of follicular architecture is preserved. "Inactivating mutations in Bruton's tyrosine kinase (BTK) in patients with follicular lymphoma (FL) have recently been reported." (PMID 36051027, 2022). "In follicular lymphoma, inactivating mutations in Bruton tyrosine kinase (BTK) lead to augmented Akt activation." (PMID 34419139, 2021).
gastric cancer (10 papers, 2014 to 2024). A primary or metastatic malignant neoplasm involving the stomach. "BTK mutation was amplified in gastric cancer, which plays a critical role in anti-cancer drug resistance." (PMID 38968283, 2024). "BTK can be a therapeutic gastric cancer target since BTK expression knockdown inhibits the gastric cancer cell growth." (PMID 38968283, 2024). "Since the expression of BTK was correlated with the prognosis of gastric cancer patients, we aimed to examine the anti-cancer activity of BTK inhibitors using gastric cancer cell lines." (PMID 37033615, 2023). "HZ-A-018 was a novel derivative of ACP-196, and it showed similar suppressive effects on phosphorylated BTK comparing with ACP-196 in gastric cancer cells." (PMID 37033615, 2023). "BTK is also found to be overexpressed in gastric carcinoma and treatment with a BTK inhibitor can reduce tumour growth." (PMID 34894949, 2022). "Knockdown BTK or inhibition of BTK with ibrutinib blocked the growth of gastric cancer cells and increased cell apoptosis." (PMID 34307353, 2021). "Since the expression of Bruton tyrosine kinase (BTK) was significantly associated with the prognosis of gastric cancer patients, we aimed to determine the anti-cancer activity of HZ-A-018, which was a novel derivative of ACP-196, in gastric cancer cells." (PMID 37033615, 2023). "Likewise, BTK inhibitors promote apoptosis in gastric carcinoma cells and reduce the growth of gastric tumor xenografts." (PMID 36903645, 2023). "In gastric cancer, BTK is over-expressed in gastric carcinoma tissues." (PMID 34307353, 2021). "Inhibiting BTK activation reversed gastric cancer cells’ resistance to docetaxel." (PMID 34307353, 2021). "BTK over-expression has been described in gastric carcinoma tissues and gastric carcinoma cells." (PMID 29561760, 2018). "However, the efficacy of BTK inhibitors in gastric cancer remains unclear." (PMID 37033615, 2023). "In addition, it has been documented that BTK is overexpressed in gastric carcinoma cells but not in normal gastric mucosa epithelial cells." (PMID 36903645, 2023).
lung carcinoma (10 papers, 2019 to 2025). "Immunohistochemical staining was utilized for identifying the expression of LDHA, CDKN3, SHC1, and BTK in 127 lung cancer samples." (PMID 40182622, 2025). "In lung cancer, the BTK inhibitor ibrutinib effectively inhibits the proliferation of some epidermal growth factor receptor (EGFR) mutant lung cancer cells by inhibiting the autophosphorylation of EGFR." (PMID 37638060, 2023). "Compared with human normal lung epithelial cell 16HBE, the expression of BTK mRNA and protein in the lung cancer cell line was significantly downregulated." (PMID 37638060, 2023). "ALK and BTK are the two major targets for inhibition of lung cancer and attraction for the receptor to develop novel drug molecules against the patient suffering from lung cancer as well as SARS-COV-2." (PMID 35356629, 2021). "We first FACSorted the lung cancer cells for BTK and determined their self-renewal capacity using sphere formation as a reveal." (PMID 34315851, 2021). "Its overexpression vector was designed to study the function of BTK in lung cancer cell lines." (PMID 37638060, 2023). "To explore whether BTK affects the migration and invasion of lung cancer cell lines, we transfected cells with BTK expression vectors to verify the role of BTK in the migration and invasion of lung cancer cell lines." (PMID 37638060, 2023). "BTK overexpression vector or empty vector was transfected into three lung cancer cell lines." (PMID 37638060, 2023). "Mechanistic insight into the other SPM group of the cohort depicted that lung cancer was the most common type of second invasive primary malignancies emerged from BTK inhibitors treatment in the study whereas NMSC was the most common SPM in the ELEVATE‐TN and ASCEND trials." (PMID 35846092, 2021). "BTK, located in the downstream of signal transduction of B-cell antigen receptor, might be a useful biomarker to predict the prognosis of lung cancer patients." (PMID 33169786, 2020). "Moreover, BTK inhibition re-sensitized lung cancer cells to either EGFR-targeted or SOC chemo-therapies disregarding EGFR/KRAS mutational status." (PMID 31200752, 2019). "Because BTK shares similarities with ETK, BTK may also be a potential target for lung cancer." (PMID 34315851, 2021). "Finally, our in vitro results indicate that among the BTK inhibitors RN486 is more powerful than Ibrutinib and AVL-292 in blocking lung cancer cell proliferation and sensitizing drug-resistant NSCLC cells to either EGFR-TKIs and SOC therapy." (PMID 31200752, 2019). "Notably, given that our data show that only the p65 isoform is expressed in lung cancer cells and tissues, a p65BTK specific antibody should be used to identify potential NSCLC patients candidate for anti-BTK therapy." (PMID 31200752, 2019). "However, the biological role of BTK in the development of lung cancer and its role in NSCLC has not been studied." (PMID 37638060, 2023).
Sjögren’s syndrome (10 papers, 2016 to 2023). "Furthermore, BTK is associated with contributing to disease pathogenesis since BTK levels of B cells were correlated with serum RF-antibody levels, and the degree of salivary gland T cell infiltration in Sjögren’s syndrome and ACPA positivity in RA patients." (PMID 34068035, 2021). "BMS-986142 is a potent and highly selective reversible small molecule inhibitor of BTK currently being investigated in clinical trials for the treatment of both RA and primary Sjögren’s syndrome." (PMID 28742141, 2017). "BTK protein was elevated in B cells of patients with primary Sjogren’s syndrome (PSjS)." (PMID 35729649, 2022). "We previously showed that in circulating B cells from primary Sjögren’s syndrome (pSS) patients with high systemic disease activity, protein expression of the BCR signaling molecule Bruton’s tyrosine kinase (BTK) was increased and correlated with T-cell infiltration in the target organ." (PMID 35563492, 2022). "Interestingly, compared to healthy individuals, elevated BTK levels were observed in circulating B cell subsets, including naive B cells, of patients with ACPA-positive RA, Sjögren’s syndrome, and active GPA." (PMID 34068035, 2021).
glioblastoma (9 papers, 2019 to 2024). The most malignant astrocytic tumor (WHO grade IV). "Previous studies have demonstrated the high expression of BTK/BMX in glioblastoma." (PMID 38589905, 2024). "Studies in glioblastoma and skin cancer found that Bruton’s tyrosine kinase (BTK) inhibitor ibrutinib induced protective autophagy, and inhibition of autophagy could increase the efficacy of ibrutinib." (PMID 32855355, 2020).
non-small cell lung carcinoma (9 papers, 2018 to 2024). A group of at least three distinct histological types of lung cancer, including non-small cell squamous cell carcinoma, adenocarcinoma, and large cell carcinoma. "A Phase 1b/2 Study investigated the efficacy of the Bruton tyrosine kinase inhibitor Ibrutinib and the PD-L1 inhibitor Durvalumab in patients with pretreated solid tumors which includes 28 non-small cell lung cancer patients." (PMID 34187403, 2021). "Increased levels of LINC01504 in the non-small cell lung cancers cell lines A549, NCI-H1650, SK-MES-1 and NCI-H226 exposed to cinnamaldehyde promoted the production of cytokine signaling 1 (SOCS1), BTG anti-proliferation factor 2 (BTG2), and Bruton tyrosine kinase (BTK)." (PMID 36499073, 2022).